MMP10 (matrix metallopeptidase 10)
Diseases named in the same sentence as MMP10 in open-access papers (continued):
Sharing a sentence is not in itself a finding about the gene and the disease.
cancer (continued). "Transcriptome analysis revealed that CHRM3 knockdown significantly reduced an array of classic factors involved in cancer invasive growth, including MMP1/MMP3/MMP10/MMP12 and CXCL1/CXCL5/CXCL8." (PMID 37744266, 2023). "Most MMPs have consistently increased gene expression across cancers, and MMP1, MMP9, MMP10, MMP11, and MMP13 are almost universally upregulated across a wide variety types of cancers." (PMID 36903626, 2023). "MMP-1 and MMP-10 primarily affect tissue integrity by degrading ECM components, thereby promoting cancer metastasis." (PMID 36980779, 2023). "These cytokines have been identified to be directly or indirectly responsible for cancer progression through remodeling of ECM by upregulating the expression of molecules such as MMP2, MMP3, MMP9, MMP10, MMP13, PLAU, ICAM1 and VCAM1." (PMID 34946170, 2021). "Although MMP1, MMP10 and PTHLH were mainly up-regulated in the 21 cancer types, the other two members GATM and ARHGEF26, were primarily down-regulated." (PMID 34301206, 2021). "The addition of benign cell lysate resulted in a significant increase of MMP9, VEGFA, ApoE, ANG, and MMP10, and the addition of cancer cell lysate resulted in a significant increase of MMP9, CA9, PAI1, ApoE, A1AT, ANG, and MMP10." (PMID 34204951, 2021). "This grouping in cluster 2 features high expression of gene cluster B genes (MMP3, MMP10, MMP13, MMP1, and MMP12) in a pattern that is relatively unique among cancer types." (PMID 31200666, 2019). "MMP1, MMP9, MMP10, MMP11, and MMP13 were almost universally upregulated across all cancers, with significant (p < 0.05) fold change (FC > 2) in ten of fifteen cancers." (PMID 31200666, 2019). "MMP-10 expression was also reported in H. pylori positive gastric biopsies and expression of MMP-10 increases with progression of cancer to later stages." (PMID 28398251, 2017). "We also detected upregulation of genes involved in cancer metastasis and cancer stemness (FOXC2, SNAI2, CXCRs, and IGF1), cell stemness (NANOG, POU5F1, and KLF4), metalloproteinases (MMP7, MMP10, and MMP13), and angiogenic factors (IL-8 and S1PR1)." (PMID 28423353, 2017). "MMP-10 (also called stromelysin-2) belongs to the MMP family and its expression correlates closely with metastasis and poor prognosis in various human cancers." (PMID 24884523, 2014). "Though MMP-10 is well characterized biochemically, compared to other MMPs, little is known about MMP-10 in human cancers." (PMID 24885595, 2014). "Based on our previous biomarker studies, we were interested in studying MMP-10, a relatively understudied MMP in cancer biology." (PMID 24885595, 2014). "Thus, Mmp10 may play a widespread role in the metastatic behavior of many types of human cancers." (PMID 22545096, 2012). "We can assume that in these circumstances the cancer cells did not limit the MMP-10 secretion to the extracellular space to such a huge extent as MMP-3." (PMID 36231910, 2022). "A panel of MMPs was analyzed in serum from PC patients—specifically, MMP-1, MMP-3, MMP-7, MMP-9, MMP-10, and MMP-12 were higher in cancer patients compared with healthy donors, showing good diagnostic accuracy, of which MMP-7 and MMP-12 achieved perfect discrimination." (PMID 30678058, 2019). "However, it appears that MMPs are important enzymes involved in local attack and metastatic PTC cancer, being reported in several studies related to different members of the MMP family, including MMP-1, MMP-2, MMP-7, MMP-9, MMP-10, MMP-13, MMP-14 and MMP-15." (PMID 30509240, 2018). "By contrast, no obvious differences in MMP-10 expression levels were found between normal and cancer epithelia." (PMID 28831065, 2017). "MMP10 and MMP13 can degrade the extracellular matrix and promote cancer metastasis and progression." (PMID 27172796, 2016).
cancer (continued). "MMP-10 was expressed in 13/21 SSCs and 11/19 BCCs only in epithelial laminin-5 positive cancer cells, while premalignant lesions were entirely negative." (PMID 11237387, 2001). "Also, MMP-10 concentrations were higher in group III–IV compared to group I–II, which suggests that, as with MMP-7 and MMP-3, this enzyme is produced at higher levels in advanced stages of cancer." (PMID 40565125, 2025). "The results demonstrate that the storage of the urine samples at room temperature for >120 min significantly increased the levels of MMP9, APOE, ANG, and MMP10, which could change the final results (positive or negative to cancer)." (PMID 39857022, 2025). "This suggests that MMP-10 may act as a marker of degenerative and inflammatory processes rather than a specific cancer biomarker." (PMID 41007705, 2025). "Transforming growth factor (TGF)-β plays a role in the invasion, metastasis and growth of cancer cells by promoting HDAC degradation and histone hyper-acetylation at the MEF2 site of the matrix metalloproteinase (MMP-10) promoter, and by activating MEF2A and up-regulating the expression of MMP-10." (PMID 37008050, 2023). "Moreover, some MMPs can prevent the apoptosis of early cancer cell, such as MMP7, MMP10 and MMP11." (PMID 36324128, 2022). "Moreover, plasma concentration of MMP-10 and MMP-3 in combination with CA 15-3 may improve diagnosis of this type of cancer." (PMID 33371324, 2020).
infection (26 papers, 2013 to 2025). The state of being infected such as from the introduction of a foreign agent such as serum, vaccine, antigenic substance or organism. "This was demonstrated by the increased susceptibility of MMP-10-deficient mice to infection by P. aeruginosa compared to wild-type mice." (PMID 39935472, 2025). "Infection with Mycobacterium tuberculosis causes cellular injury by increasing the production of MMP-10, MMP-1, and MMP-7 in macrophages." (PMID 34944659, 2021). "Matrix metalloproteinase 10 (MMP-10), also known as stromelysin-2 or transin-2, is released by macrophages and, to a lesser extent, epithelial cells in most tissues upon injury or infection." (PMID 40343765, 2025). "These included cytokines and cytokine receptors (Il11, Tnfsf18, and Ackr4), genes involved in infection (Ptgs2 and Heyl), cell adhesion and migration (Spon2 and Mmp10)." (PMID 35293863, 2022). "In conclusion, we identified a group of cytokines, including IL-17C, MMP-10, FGF-23, CCL23, FGF-19 and CXCL5 that are differentially regulated during asymptomatic and mild symptomatic infections and are known to be associated with tissue repair functions." (PMID 35479098, 2022). "MMP-10 (or stromelysin-2) plays a key role in the host response to environmental stimuli, and its expression is induced following injury, infection, or transformation." (PMID 36031900, 2022). "T cells from CD4+ and CD8+ lineages are essential to control bradyzoites containing cysts at the brain, T cells expressing MMP-10 are present at the brain after 21 days of infection, while T cells expressing MMP-8 are observed at 28th day of infection." (PMID 28955329, 2017). "The expression of MMP-1 and MMP-10 was significantly upregulated following induction by H. pylori infection (P<0.05), with significant effects occurring following infection for 12 and 6 h, respectively." (PMID 25120597, 2014). "However, when the body was exposed to external stimuli, including injury and infection, the expression of MMP10 significantly increased." (PMID 40435311, 2025). "After infection with Adv-MMP-10 (10 MOI) for 48 and 72 h, PASMCs generated active MMP-10." (PMID 34975336, 2022). "After infection with LV-Wincr1, expression of Mmp10 increased dramatically compared to the control." (PMID 29209359, 2017). "Although nothing is known about the role for MMP1 or MMP10 in CF, our data suggest that these two enzymes may be involved in tissue damage related to excessive inflammation and may contribute to infection-related CF pathology." (PMID 26485688, 2015). "The protein expression of seven proteins (CD8A, ST1A1, AXIN1, FGF-5, MMP-10, HGF, SIRT2) was significantly decreased and the protein expression of two proteins (MMP-1, TNFRSF9) was significantly increased in caspase-1-deficient cells compared to Cas9 cells following HK1651 infection." (PMID 40137780, 2025). "The combination treatment with both TMAO and CFT073 had significant additive effects on the release of PD-L1 and STAMBP and synergistic effects on the release of CDCP1, uPA, AXIN1, MMP-10, and CD40 compared to CFT073 infection alone." (PMID 37111409, 2023). "In our previous in vitro study of E. tenella infected chicken macrophages, MMP9 expression was transiently up-regulated at 12 hpi while MMP10 and MMP17 expression was up-regulated later in the infection at 48–72 hpi (unpublished observation)." (PMID 34521339, 2021). "After infection, particularly at the 6 h and 8 h time points, CSF2, CCL2, MMP1, and MMP10 proteins were expressed at higher levels in CF than CTRL cells, although the differences were not statistically significant." (PMID 26485688, 2015). "There was a significant increase in cell proliferation after infection with Adv-MMP-10 (10, 20 MOI) compared to that in non-infected cells at 48 and 72 h." (PMID 34975336, 2022).
infection (continued). "Vitamin D therapy of PBMCs decreases the MMP-10, MMP-1, and MMP-7 expression while increasing the TIMP-1 expression, indicating its critical function in preventing cellular injury and providing symptom relief while having an infection." (PMID 34944659, 2021). "Infection with V. atypica resulted in a decrease in the concentration of PDGF-AA, VEGF, and MMP-10." (PMID 34230496, 2021). "Similarly, we also found an up regulation of tissue remodeling factors induced by extracellular infection with WCH-SK2WT (MMP1, MMP2, and MMP10) and WCH-SK2SCV (MMP1 and MMP9) as well as intracellular infection with WCH-SK2WT (MMP9)." (PMID 28083514, 2016). "However, infection or inflammation may amplify the action of LMW-HAs via interactions with hyaladherins, leading to an increase in the secretion of cytokines (TNF-α, IFN-β, IL-6), chemokines (IL-8), ROS, or enzymes (NE, MMP-9, MMP-10, MMP-12)." (PMID 35625586, 2022).
cardiovascular disease (9 papers, 2013 to 2025). "While previous studies have implicated CTRC, OSM, and MMP-10 in cardiovascular disease, our study is the first to implicate them in exacerbations of COPD." (PMID 40343765, 2025). "Recent studies have associated MMP-10 with cardiovascular diseases and inflammatory conditions that contribute to ECM degradation and vascular remodeling." (PMID 40278353, 2025). "Of interest, circulating MMP10 levels have been correlated with markers of inflammation and increased atherosclerotic plaques in patients with elevated cardiovascular disease risk." (PMID 23691065, 2013). "Among these proteins, matrix metalloproteinases such as MMP-7 and MMP-10 have emerged as key regulators in the development of cardiovascular diseases." (PMID 40563493, 2025). "This NOX5-derived MMP-10 secretion may have consequences in different cardiovascular diseases in vivo." (PMID 39456453, 2024). "Taken together, these studies provide compelling evidence for the involvement of MMP-10 and MMP-7 in cardiovascular disease pathogenesis in multiple arterial beds." (PMID 40563493, 2025).
inflammation (6 papers, 2015 to 2025). Aberrant reaction of the microcirculation characterized by movement of fluid and leukocytes from the blood into extravascular tissues. "IL18rap, MMP10 and Irs1 have been recently shown to play a role in the pathogenesis of CNS inflammation." (PMID 25993608, 2015).
adenocarcinoma (5 papers, 2001 to 2025). A common cancer characterized by the presence of malignant glandular cells. "For instance, the expression of MMP 10 is regulated through the JAK2/STAT3 signaling in adenocarcinomas." (PMID 30220965, 2018). "For instance, IL-6 regulates MMP 10 through JAK2/STAT3 signaling in adenocarcinomas." (PMID 30220965, 2018). "Here we confirmed those findings, and we observed a dramatic increase in Mmp3, Mmp10, and Mmp13 expression in CAC tissue relative to normal tissue; their expression was increased in dysplastic tissues and adenocarcinoma tissues and particularly in inflamed tissues." (PMID 25742789, 2015).
bacterial infection (3 papers, 2024 to 2025). "MMP-10 is elevated in the CF lung and has been suggested to have a protective role against bacterial infection by regulating macrophage activation." (PMID 39935472, 2025).
metabolic disorder (2 papers, 2024). "Pathway-based enrichment analysis of these differential metabolites suggested a metabolic disorder involving multiple amino acids indicated by MMP10." (PMID 39393173, 2024). "Elevated levels of MMP-10 in other inflammatory and metabolic disorders also support its role in PCOS-related inflammation and metabolic dysregulation." (PMID 39691364, 2024).
respiratory diseases (2 papers, 2019 to 2020). "The top ten genes (Clca1, Chil4, Itln1, Tff1, Muc5ac, Clca3b, Chodl, Pla2g4c, Mmp10, and Stac2) with the highest fold change are involved in various inflammatory responses and respiratory diseases." (PMID 33066398, 2020).
connective tissue disease (1 paper, 2025). "Concerning early connective tissue disease (CTD)-ILD+ diagnosis, increased MMP-7, MMP-9, MMP-10, and MMP-12 levels were found in RA-ILD+ and SSc-ILD+ patients in relation to RA-ILD- and SSc-ILD- patients, respectively." (PMID 39979794, 2025).
intestinal ulcer (1 paper, 2020). "In an DSS-induced mouse model of UC, expression of MMP-3 (stromelysin-1) and MMP-10 (stromelysin-2) increased in gut and intestinal ulcer tissues." (PMID 32486445, 2020).
neurodegenerative disease (1 paper, 2012). A disorder of the central nervous system characterized by gradual and progressive loss of neural tissue and neurologic function. "There is much less known about the role of MMP10 MMP10 in neurodegenerative diseases." (PMID 23185624, 2012).
MMP10 also shares sentences with these, for which no sentence is quoted: malaria (6 papers); inflammatory bowel disease (4); chronic gastritis (3); retinopathy (3); vascular dementia (3); bladder transitional cell carcinoma (2); breast invasive carcinoma (2); cerebral malaria (2); delirium (2); liver fibrosis (2); Lyme disease (2); actinic keratosis (1); amyloid (1); amyotrophic lateral sclerosis (1); Arterial thrombosis (1); basal cell carcinoma (1); Bowen's disease (1); calcification (1); calcinosis (1); cardiac conduction disorders (1); cerebrovascular disease (1); cervical dysplasia (1); cervical squamous cell carcinoma (1); chorioamnionitis (1); chronic obstructive pulmonary disease (1); coagulopathy (1); colonic (1); colorectal adenocarcinoma (1); colorectal adenoma (1); dyslipidemia (1).
A further 47 diseases each share a sentence with MMP10 in 1 paper.